CXCR3 (C-X-C motif chemokine receptor 3)
Diseases named in the same sentence as CXCR3 in open-access papers (continued):
Sharing a sentence is not in itself a finding about the gene and the disease.
liver disease (11 papers, 2011 to 2025). "We thus focused our efforts on understanding the molecular mechanism underlying the accelerated liver disease in HCV/HIV-1-coinfected patients by studying the regulation of the CXCR3-associated chemokines." (PMID 24516541, 2014). "We conclude that in people living with HIV and HBV, liver disease is associated with elevated intrahepatic mRNA for CXCL10 and CXCR3." (PMID 32898182, 2020). "We then explored the possibility of increased ILC2 infiltration in liver diseases by examining the expression of liver homing CXCR3 and biliary homing CCR6 chemokine receptors by peripheral blood ILC of normal and autoimmune liver disease patients." (PMID 29261670, 2017). "A CXCR3-dependent mechanism has been shown to be important in Treg recruitment to sites of inflammation in the periphery and central nervous system as well as in an experimental model of liver disease." (PMID 30915078, 2019). "Recruitment of CXCR3-expressing lymphocytes and NK cells to sites of liver inflammation by the CXCL9–11 chemotaxis has been proposed for several liver diseases." (PMID 39980752, 2025). "For cholangitis, CXCR3 is likely to not only directly regulate CD8+ T cells and their IFN-γ production to ameliorate liver disease but also regulate CD4+ T cells to affect the function of CD8+ T cells indirectly." (PMID 29868034, 2018). "Human liver-infiltrating Th17 expressed high levels of chemokine receptors, CCR6 68 ± 11% (mean ± SD), CXCR3 47 ± 11%, and CCR4 44 ± 13%, irrespective of the cause of liver disease." (PMID 22796894, 2012). "While additional research is required to better define the exact mechanism by which CXCR3+CXCR6+ γδT cells exert their protective role, findings from the current study provide more insight into liver-resident lymphocytes and provide novel strategies for the treatment of diverse liver diseases." (PMID 35126348, 2021).
breast tumors (10 papers, 2015 to 2024). "The Ras/MAPK transcriptional signature was highly associated with expression of CXCL1/2/8 and CSF1/2/3 across TNBC/basal-like breast tumors, while T cell–recruiting CXCR3 chemokines were negatively associated with Ras/MAPK activity." (PMID 32634121, 2020). "Therefore, SRC-3 inhibition activates the Cxcl9/Cxcr3 axis, causing an antitumor immune microenvironment by recruiting cytotoxic immune cells into breast tumors." (PMID 36316775, 2022). "CXCR3 short-stranded RNA expressed in breast tumor cells effectively controls breast tumor metastasis." (PMID 36479091, 2022). "Our data is in line with a recent study in which it was reported that Cxcr3−/− mice show an abundance of M2 macrophages in breast tumors." (PMID 34328416, 2021). "Here in our study of mouse models of breast tumor metastasis, targeting mouse CXCR3, the CXCR3A form, decreased tumor metastasis." (PMID 26485767, 2015). "AMG487, a minor molecular weight CXCR3 antagonist, may inhibit the possible spontaneous metastasis of breast tumors to the lungs via a systemic route of administration." (PMID 36479091, 2022). "Antagonism of CXCR3 with the small molecule AMG487 in mice bearing syngeneic subcutaneous breast tumors resulted in decreased lung metastasis, but did not affect growth of the primary tumor." (PMID 25629162, 2015).
leukemia (10 papers, 2017 to 2026). A malignant (clonal) hematologic disorder, involving hematopoietic stem cells and characterized by the presence of primitive or atypical myeloid or lymphoid cells in the bone marrow and the blood. "Both PSGL-1 and CXCR3 have been implicated in the migration of leukocytes across the blood–CSF barrier and may play a similar role in leukemia." (PMID 28491865, 2017). "The levels of CXCR3 were higher in CD4+CD8+ DP cells of leukemia-bearing mice compared with control animals." (PMID 41129238, 2026). "CXCL10hiCXCL11hi zones may represent exclusive leukemia-positioning niches where B-ALL cells may also contribute to CXCL11 expression presumably relevant for positioning of CXCR3+CXCR7+ LICs and suitable for immune scape." (PMID 34737747, 2021). "We then attempted to achieve a preliminary exploration of the pathogenesis of leukemia through the study of five prognostic genes (TNF, CXCR3, CD4, PIK3CA and CALR)." (PMID 38671491, 2024). "Restored expression of Tbet and a Tbet dependent increase in IFN-γ and CXCR3 expression was also found after combined check-point blockade (PD-1, CTLA-4, and LAG-3) in a murine leukemia model." (PMID 33193386, 2020). "As we know, CXCR3’s ligands included CXCL10 (IP-10) and CXCL11 (I-TAC), and few researches about CXCL9.CXCL10 was selected through stimulating leukemia U937cell lines from the DNA pool by Luster who comes from American." (PMID 30973890, 2019). "While the role for IL-15 in leukemia proliferation and survival is discussed in the next section, IL-15 also upregulates p-selectin glycoprotein ligand-1 (PSGL-1) and CXCR3 levels in leukemia cells." (PMID 28491865, 2017). "In leukemia, this was observed in a study involving pediatric patients with ALL, with CXCL10 inducing chemotaxis of leukemic cells that expressed CXCR3, and also decreased chemotherapy-induced apoptosis in the leukemic cells CXCR3+." (PMID 34335758, 2021). "Eμ-Tcl1 Tg leukemias exhibited heterogeneous surface staining for CXCR4, CXCR5 and CCR7, but were negative for CXCR3." (PMID 27843137, 2017).
Sepsis (10 papers, 2012 to 2025). Sepsis is defined as life-threatening organ dysfunction caused by a dysregulated host response to infection. "Compared to wild-type mice, CXCR3-deficient mice show less systemic cytokine production, attenuated physiologic dysfunction and improved survival during severe sepsis caused by cecal ligation and puncture (CLP)." (PMID 24890566, 2014). "Large numbers of CXCR3+ NK cells migrate from the spleen and blood into the peritoneal cavity during CLP-induced sepsis, a phenomenon that is ablated in CXCR3-deficient mice as well as in mice treated with neutralizing antibodies against CXCR3." (PMID 24890566, 2014). "Our recent studies show that CXCR3 is an important regulator of NK cell trafficking during severe sepsis caused by cecal ligation and puncture (CLP)." (PMID 22992408, 2012). "The studies also show the potential of CXCR3 blockade as a therapeutic approach to decrease the severity of sepsis during its acute phase." (PMID 34484417, 2021). "Our findings also demonstrate that CD43 drives a TH1 phenotype, as CD43-/- demonstrate significantly decreased IL-2+ CXCR3+ CD4+ (TH1-like) cells with a concomitant increase in IL-4+ CCR4+ CD4+ (TH2-like) cells in sepsis." (PMID 30226896, 2018). "Our previous studies examined outcome, systemic inflammation and bacterial clearance in CXCR3 knockout mice and in mice treated with anti-CXCR3 immunoglobulin prior to the initiation of sepsis." (PMID 22992408, 2012). "In the present study, the effect of CXCR3 blockade, when administered after the initiation of sepsis, was investigated." (PMID 22992408, 2012). "More recently, evidence has emerged that supports a role for CXCR3 activation in the pathogenesis of sepsis." (PMID 22992408, 2012). "Further work is needed to fully define how CXCR3 is activated and mediates inflammatory and physiological changes during severe sepsis." (PMID 22992408, 2012). "This study shows that inhibition of CXCR3 activation using blocking antibodies is efficacious in reducing the severity of CLP-induced sepsis." (PMID 22992408, 2012). "Further studies are needed to fully define the protective mechanisms of CXCR3 blockade during sepsis and to determine its value as an approach to limit injury and improve outcome during sepsis." (PMID 22992408, 2012). "The findings of the present study extend our previous observations by showing the potential of CXCR3 blockade as a therapeutic approach to decrease the severity of sepsis during its acute phase." (PMID 22992408, 2012). "Furthermore, CXCR3 signaling has been shown to play a crucial role in the murine neonatal response to sepsis." (PMID 25573892, 2015). "Recently, a role for CXCR3 activation in the pathogenesis of severe sepsis has been proposed." (PMID 24890566, 2014). "Few studies have examined the effects of CXCR3 blockade during sepsis." (PMID 22992408, 2012). "The goal of the study was to determine whether administration of anti-CXCR3 IgG after the initiation of sepsis will attenuate the pathobiology of sepsis and improve survival compared with mice treated with nonspecific IgG." (PMID 22992408, 2012). "As a CXC chemokine, IP-10 can specifically bind to chemokine (C-X-C motif) receptor 3 (CXCR3) to promote T lymphocyte migration and neutrophil infiltration, and the IP-10–CXCR3 axis has been suggested to be critical for exacerbating the pathological process of sepsis." (PMID 37701855, 2023). "Furthermore, CD43-/-septic mice exhibited a prominent Th2 skewing following sepsis relative to WT septic mice, as evidenced by a significant decrease in the frequency of IL-2+ CXCR3+ TH1 cells as a significant increase in the frequency of IL-4+ CCR4+ TH2 cells." (PMID 30226896, 2018).
Sepsis (continued). "In contrast to the cell death–induced lymphopenia hypothesis, Herzig and colleagues demonstrated that in experimental peritoneal sepsis, murine NK cells migrate into the peritoneal cavity via a chemokine (C-X-C motif) receptor 3 (CXCR3)-induced mechanism, resulting in peripheral blood lymphopenia." (PMID 28287491, 2017). "Through searching the sepsis-related publication of the key genes, CCR7, CXCR3, FYN, CEACAM1, CD81, AMPH, HLA-DMA, and G protein-coupled receptors (GPR18) were considered to be key genes." (PMID 34484417, 2021). "CD43-/- septic mice exhibited a decrease in the frequency of IL-2+ CXCR3+ CD4+ cells relative to CD43-/- sham controls, suggesting a sepsis- related shift away from a Th1 phenotype." (PMID 30226896, 2018). "Evidence indicates that CXCR3+ NK cells migrate into the inflamed peritoneal cavity from blood and spleen early during the course of CLP-induced sepsis." (PMID 24890566, 2014). "In our previous studies we demonstrated that CXC chemokine receptor 3 (CXCR3) participates in the regulation of lymphocyte trafficking during cecal ligation and puncture (CLP)-induced sepsis." (PMID 22992408, 2012). "However, our previous studies show that trafficking of CXCR3+ T lymphocytes into the peritoneal cavity is minimal in the initial 16 hours after CLP and that CXCR3 deficiency or blockade does not alter T-cell trafficking into the primary site of infection during CLP-induced sepsis." (PMID 22992408, 2012). "As suggested in S2 Fig where the phenotype of cells obtained from sham or CLP hosts was compared, sepsis also did not change the expression of CXCR3 on P14 TCIRCM cells used in this assay." (PMID 28910403, 2017). "• Treatment with anti-CXCR3 IgG up to 6 hours after CLP will decrease systemic cytokine production, attenuate physiologic dysfunction and improve survival in a clinically relevant experimental model of severe sepsis." (PMID 22992408, 2012). "CXCR3, CCR7, HLA-DMA, and GPR18 might be correlated with the sepsis mechanism." (PMID 34484417, 2021). "CXCR3, CCR7, HLA-DMA, and GPR18 might participate in the mechanism of CAP with sepsis." (PMID 34484417, 2021). "Whether nonpeptidergic CXCR3 inhibitors are efficacious in experimental models of sepsis remains to be determined." (PMID 22992408, 2012). "However, the mechanisms by which CXCR3 alters NK cell and NK T-cell function during sepsis and the systemic inflammatory response syndrome is not completely understood." (PMID 22992408, 2012). "Hepatic CXCR3+ NK cells and NK T cells are therefore likely to become activated during CLP-induced sepsis but do not migrate out of the liver." (PMID 22992408, 2012). "In addition, large numbers of CXCR3+ NK cells are present within the liver, lung and bone marrow and their numbers do not change significantly during CLP-induced sepsis." (PMID 22992408, 2012).
dengue (9 papers, 2007 to 2024). "Furthermore, CXCR3-deficient mice showed an increased mortality rate (associated with higher viral load) after West Nile Virus (WNV) or dengue virus infection that can also lead to neuropathic diseases." (PMID 30876387, 2019). "A significant increase in CXCR3+ dengue-specific CD8+ Tcm at day 35 in the PepGNP-Dengue group indicates that cells with tissue-homing potential were generated." (PMID 38128414, 2024). "The frequency of Th1-like Tregs (CXCR3+CCR4−CCR6− Tregs) was increased in dengue patients compared to HD control (P = 0.003)." (PMID 38752787, 2024). "Further work will be required to determine if CXCR3+ TFH cells provide help to support the production of efficient neutralising antibody responses that protect against severe dengue disease symptoms." (PMID 37055751, 2023). "In a dengue intracerebral mouse infection models, CXCR3−/− and IP10−/− mice both had higher mortality rate than wild type mice after infection, indicating that IP-10 and CXCR3 receptors are part of the host defense mechanism, most likely in recruitment of T cells to the infection site." (PMID 18060089, 2007). "CD8+ TEM/TEMRA cells in blood from dengue-infected adults during acute phase expressed high levels of CLA (cutaneous lymphocyte-associated antigen), a skin homing receptor, and chemokine receptors CXCR3, CCR5, and CXCR6, which support T cell migration to inflamed tissues." (PMID 31244855, 2019). "Treatment of purified naïve CD4+ T cells with EVs derived from severe dengue plasma drove CD4+ proliferation toward specific subtypes and modulated surface receptor CXCR3 and CCR6 expression." (PMID 37982662, 2023). "More interestingly, plasmablasts and plasma cells had significantly higher frequencies of CXCR3 and CCR2 expression in dengue patients than healthy individuals." (PMID 30149800, 2018). "Our detailed phenotypic analysis showed an increase in the frequency of Th1-like Tregs (CXCR3+CCR4−CCR6− Tregs) in all dengue patients, irrespective of disease severity." (PMID 38752787, 2024). "Observed increases in D-dext+CD8+ total, Tcm, TemRA, and CXCR3+ Tcm memory cells in the PepGNP-Dengue group were apparent for the LD but not the HD group." (PMID 38128414, 2024).
experimental autoimmune encephalomyelitis (9 papers, 2013 to 2025). An autoimmune demyelinating disease of the central nervous system that is produced experimentally in animals by the injection of homogenized brain or spinal cord in Freund's adjuvant. "Consistent with our in vitro data, genetic ablation of Caveolin-1 reduces infiltration of CXCR3+ CD4+ T cells into the CNS in experimental autoimmune encephalomyelitis." (PMID 40063988, 2025). "Chung & Liao reported that CXCR3 signaling in glial cells mitigates experimental autoimmune encephalomyelitis by limiting the development of a pro-Th17 cytokine environment and decreasing the infiltration of Th17 cells into the CNS." (PMID 38259497, 2023). "In another study, the authors demonstrated a protective role for CXCR3 in experimental autoimmune encephalomyelitis (EAE) using C57BL/6 mice." (PMID 36704563, 2022). "It had been implicated that CXCR3 is highly expressed on pro-inflammatory human CD4+Th17 cells, “pathogenic” human Th1/17 cells, and myelin oligodendrocyte glycoprotein-specific CD4+ T cells in experimental autoimmune encephalomyelitis mice in combination with other biomarkers." (PMID 26150899, 2015). "For instance, C-X-C motif chemokine receptor 3 (CXCR3) plays an important role in T cell recruitment to the CNS by binding with C-X-C Motif Chemokine Ligand 10 (CXCL10), CXCL9, and CXCL11 in experimental autoimmune encephalomyelitis (EAE)." (PMID 35674826, 2022). "CXCL16 has also been shown to regulate T cell homing to the CNS in experimental autoimmune encephalomyelitis (EAE), and it was recently shown in this model that immature myeloid cells expressing CXCL16 redirect CXCR3 + CXCR6+ and myelin-specific T cells from CNS to lymph nodes." (PMID 24069377, 2013).
Stroke (9 papers, 2012 to 2024). Sudden impairment of blood flow to a part of the brain due to occlusion or rupture of an artery to the brain. "A panel of genes encoding chemokine receptors, including Ccr10, Cxcr6, and Cxcr3, was upregulated in circulating CD8+ TRLs after stroke." (PMID 35912857, 2022). "It has been reported that IP-10/CXCR3 had an important part in the pathological process of stroke patients and experimental cerebral ischemia." (PMID 31881846, 2019). "The authors reported that worse stroke severity at the acute stage could result in higher CD8+CXCR3(CD183)+CD62L+ T cell levels." (PMID 35912857, 2022). "A recent clinical study in 210 stroke patients and 87 healthy controls provides evidence that circulating CD8+CXCR3(CD183)+CD62L+ T cells may be linked to initial stroke severity." (PMID 35912857, 2022). "If we get the positive results, CXCR3 may be the possible target for both stroke and stroke-infection." (PMID 31881846, 2019). "Chemokine IP-10 may be a diagnostic or prognostic biomarker (significantly increased in plasma) in ischemic stroke-infection and its specific receptor CXCR3 may be the alternative targets for stroke-infection therapy in the near future." (PMID 31881846, 2019). "Several chemokine receptors (eg CXCR1, CXCR2, CXCR3) are expressed in oligodendrocytes and show increased expression in MS, stroke and amyotrophic lateral sclerosis, and have been implicated in disorders in which myelin damage is associated with immune activation in the CNS." (PMID 29588250, 2018). "The chemokine receptors CCR2, CCR5, CXCR2, CXCR3, CXCR4 and CX3CR1 are constitutively expressed in the human brain, and their expression is enhanced under pathological conditions, including stroke and neurodegenerative diseases like HIV-associated dementia (HAD) and Alzheimer’s disease (AD)." (PMID 23210607, 2012). "However, the function of the CXCR3/CXCL10 axis in stroke remains unclear." (PMID 35912857, 2022). "CXCR3, the receptor of CXCL10, is known to reduce brain infarction and attenuate BBB disruption in stroke." (PMID 35091962, 2022). "Supporting the brain-homing properties of CXCR3/CXCL10 for CD8+ TRLs after stroke, CD8+ TRLs failed to infiltrate ischemic brain in Cxcl10-KO and Cxcr3-KO mice." (PMID 35912857, 2022). "Cxcr3 KO in CD8+ TRLs or the absence of CXCL10 in the stroke lesions impairs brain infiltration by CD8+ TRLs and hinders their neuroprotective properties." (PMID 35912857, 2022). "Flow cytometric analysis showed that the WT, but not Cxcr3-KO CD8+CFSE+ TRLs, entered the ischemic brain 3 days after stroke." (PMID 35912857, 2022).
Alzheimer disease (8 papers, 2012 to 2025). A progressive, neurodegenerative disease characterized by loss of function and death of nerve cells in several areas of the brain leading to loss of cognitive function such as memory and language. "Additionally, CXCR3 expression in neurons and neural processes in Alzheimer’s disease (AD) patients is correlated with AD-related pathological changes." (PMID 40786052, 2025). "Likewise, Cxcr3 signaling in an APP/Ps1 mouse model of Alzheimer’s disease has been shown to increase plaque formation and reduce microglial phagocytosis of plaques." (PMID 39091874, 2024). "In an Alzheimer's disease model, the absence of CXCR3 was associated with attenuated microglial reactivation, reduced inflammatory factors, and improved cognition." (PMID 37438982, 2023). "In Alzheimer’s patients, while CXCR3 expression level remained unaltered, its ligand CXCL10 was found to be upregulated in astrocytes, which remained associated with senile plaques, characteristic of Alzheimer’s disease." (PMID 35794867, 2022). "CXCR3 is constitutively expressed on neurons and neuronal processes, along with markedly elevated CXCL10 in astrocytes in the brains of people with Alzheimer’s disease." (PMID 34835465, 2021).